LINC03041 (long independently transcribed non-coding RNA 3041)
Synonyms: C9orf92; Em:AL513424.1
Gene: Long non-coding RNA gene on chromosome 9 (16,203,935 to 16,410,990, reverse strand). Ensembl gene ENSG00000205549.
Diseases named in the same sentence as LINC03041 in open-access papers:
LINC03041 is named in the same sentence as 7 diseases in open-access papers, as found by Europe PMC text mining. Sharing a sentence is not in itself a finding about the gene and the disease.
LINC03041 shares sentences with these, for which no sentence is quoted: cancer (1 paper); connective tissue tumors (1); hypothyroidism (1); lipoma (1); lung carcinoma (1); melanoma (1); tumor (1).